CDK9 (cyclin dependent kinase 9)
Diseases named in the same sentence as CDK9 in open-access papers (continued):
Sharing a sentence is not in itself a finding about the gene and the disease.
tumor (continued). "Expression of CDK9 in HepG2, MHCC-97H, HLE, Huh7, and Hep3B cells was significantly higher than that in tumor cells HLE and normal cells LO2, and the CDK9 inhibitors LDC067 and PHA767491 inhibited the proliferation of HepG2 in vitro and in vivo, respectively." (PMID 39654621, 2024). "Multiple CDK9 inhibitors, including fadraciclib, AZD-4573, and CDKI-73, have been created and have shown substantial anti-tumor effects in preclinical research." (PMID 39404419, 2024). "In HepG2-derived xenograft model and a PDX model of HCC, CDK9 inhibitor, PHA767491 and oroxylin A (OA) from Scutellaria baicalensis significantly decreased the protein expression of CDK9, PINK1, PRKN, p-SIRT1, FOXO3 and BNIP3 in tumor tissues." (PMID 37670307, 2023). "We found that dual CDK9/PI3K inhibition slowed proliferation of DLBCL cell lines and primary cells in vitro as well as restricted tumor growth in vivo." (PMID 36998071, 2023). "Simultaneously, we observed that the expression levels of CDK9 and DDX56 were both high in THCA tumor tissue (Wilcoxon test, p < 0.05)." (PMID 36568395, 2022). "When used together, CDK9 and BRD4 inhibitors impede transcription of anti-apoptotic genes and c-MYC oncogene, suppressing tumor proliferation." (PMID 35092513, 2022). "Immunohistochemical analysis of the tumour tissues showed changes in the protein expression of MMP9, vimentin, Bax, Bcl‐2, p‐p65, CDK9, MMP2, N‐cadherin and MIF." (PMID 35060345, 2022). "The inhibition of CDK9, induced by MC180295 led to dephosphorylation of BRG1, which contributed to the restoration of tumor suppressor gene expression." (PMID 35092513, 2022). "In tumor cells, c-MYC directly activates RBPJκ and subsequent target genes in a NOTCH activation-independent manner, mediated by CDK9, a component of positive transcription elongation factor b (P-TEFb)." (PMID 35215234, 2022). "Upon tumor manifestation, we treated mice with NVP-2 (2.5 or 5 mg/kg, once per day, 5 d per week) or vehicle followed by an assessment of CDK9 inhibition (pSer2), tumor response (ultrasound, liver enzymes, and histology), and overall survival." (PMID 35442775, 2022). "Meanwhile, on the TCGA portal, we found that CDK7, CDK8, CDK9, CDK12, CDK19, and CDK20 mRNA levels were differentially expressed in the 4 molecular tumor subtypes." (PMID 33686962, 2021). "Of note, CDK9 targeting by dinaciclib in MB also mediates the degradation of the oncogenic MYC, as has already been observed in different tumour settings." (PMID 33686114, 2021). "Lastly, 21e also inhibited the tumor growth of a mouse xenograft model derived from the NSCLC cell line H1299, once more validating the significance of CDK9 in lung cancer." (PMID 34062779, 2021). "The patent includes 148 compounds with the general formula 39, most of which show CDK9 IC50 value <10 μM and supress the viability and proliferation of tumour cells with IC50 of 0.4 μM." (PMID 33632038, 2021). "The copy number analysis of CCA tumor samples indicated a gain in CDK2 (22.8%), CDK5 (14.3%), and CDK9 (5.7%)." (PMID 33116269, 2020). "Another tumorigenic feature of Myc is looping to tumor-specific super-enhancers (sites defined by multiple enhancers abnormally bound by a plethora of transcription factors, such as BRD4 and CDK9)." (PMID 33322239, 2020). "The highly selective CDK9 inhibitor, AZD4573, induced apoptosis and subsequent cell death in hematologic cancer models in vitro and favored tumor regression in tumor xenografts in vivo, through the indirect inhibition of Mcl-1." (PMID 32455818, 2020). "Seliciclib is an ATP competitive inhibitor of CDK2, CDK7 and CDK9, with an average anti-proliferative activity (IC50) in tumor cells of around 15 μM." (PMID 32645016, 2020). "A recent study demonstrated that CDK9-specific inhibitor, MC180295, downregulates MYC and leads to reactivation of epigenetically silenced tumor suppressor genes." (PMID 33322239, 2020).
tumor (continued). "Together, these data demonstrate that simultaneous inhibition of CDK9 and BRD4 acts synergistically on suppressing tumor proliferation." (PMID 29156698, 2017). "miR-874-3p has been consistently shown in various tumour types to be a tumour suppressive miRNA through regulation of STAT3, CDK9 and E2F3 expression." (PMID 28076852, 2017). "Given the increased cell cycling of tumor cells, we reasoned that the pharmacological inhibition of CDK2 and CDK9 would increase the sensitivity of NB cells to chemotherapeutic agents." (PMID 27378523, 2016). "More importantly, dinaciclib significantly inhibited NB tumor growth in two orthotopic mouse models by blocking CDK2 and CDK9 activity and inducing tumor cell death." (PMID 27378523, 2016). "More importantly, dinaciclib demonstrated in vivo anti-tumor efficacy in multiple NB mouse models via inhibiting CDK2 and CDK9 activity." (PMID 27378523, 2016). "Dinaciclib significantly inhibited the cyclinT1, CDK9, c-MYC, cyclin B1 and survivin protein expression levels in tumor tissues (n=3)." (PMID 27486754, 2016). "Consistently, dinaciclib blocked CDK2 and CDK9 activity by abolishing the phosphorylation of Rb (Ser807/811) and RNAP II (Ser2) and ultimately induced PARP cleavage in those tumor tissues." (PMID 27378523, 2016). "Combined CDK9 and EGFR inhibition disrupted transcriptional programs, enhanced TNBC cell death in vitro, and acted synergistically to reduce tumour growth in PDX and Hs578T xenograft models, although this combination was also associated with increased toxicity." (PMID 41505030, 2026). "Our study addresses a critical gap in understanding how CDK9 specifically facilitates Ser2 phosphorylation in tumor cells without significant elevation in expression, offering a more comprehensive model of transcriptional regulation in LUAD." (PMID 40860160, 2025). "As a tumor suppressor, SIRT2 maintains genome stability and prevents oncogenic transformations by regulating the DNA damage response through deacetylating key components like ATRIP (ATR-interacting protein) and CDK9 (Cyclin-dependent kinase 9)." (PMID 40710366, 2025). "To avoid potential side effects, we suggested the alternative use of DT2216, a PROTAC targeting BCL-xL for degradation in tumor cells but not in platelets, and dinaciclib, a CDK9 inhibitor that potently suppresses MCL-1." (PMID 40113795, 2025). "The CDK9 expression levels were determined by immunohistochemistry in 46 tumor and 12 nontumor liver tissues from postchemotherapy surgical specimens." (PMID 37729391, 2024). "Using our newly established CDC preclinical models, coupled with drug screening, we identified a CDK9 inhibitor, LDC000067, as a promising candidate which could specifically target CDC tumor growth and extend survival." (PMID 39122888, 2024). "For validation studies, the specific CDK9 inhibitor NVP-2 and the chemically distinct inhibitor AZD4573 known to induce tumor regression in a PDX model of AML and now being examined in phase II trials for advanced hematological malignancies (NCT03263637, NCT04630756) were used." (PMID 37801608, 2024). "CDK9 staining was weak in nontumor samples, while it was present at heterogeneous intensities across the tumor samples." (PMID 37729391, 2024). "Notably, here we report on a newly developed, highly specific CDK9 inhibitor, VCC972839:01 (VC-1), with comparable anti-tumour activity to dinaciclib." (PMID 38769311, 2024). "Here, we characterized the anti-tumor efficacy of MC180295, a newly developed CDK9 inhibitor." (PMID 38172923, 2024). "Furthermore, CPYPP and curcumin significantly suppressed tumor growth, tumor weight, CDK7, and CDK9 activities in an OECM1-DTX orthotopic mouse model, consistently with upregulated proteasome activity and sustained body weight." (PMID 38858714, 2024). "We also showed that CDK9 inhibition could increase CD45 + cell numbers and percentages of CD3 + T cells in the tumor environment." (PMID 38172923, 2024).
tumor (continued). "Besides potent activities against CDK9 and GSK-3β signal pathways, this compound also effectively suppressed tumor growth in a xenograft mice model with little adverse effects." (PMID 39404419, 2024). "Most selective CDK9 inhibitors, such as AZD4573, atuveciclib, VIP152, A-1592668 and JSH-150, have been shown to reduce tumor growth, mainly in hematological malignancies, in vitro and in vivo, and some of them have already progressed to phase I clinical trials." (PMID 37272701, 2023). "Spearman’s correlation coefficient showed a weak to moderate negative correlation between CDK9 expression and tumor stage, grade, size, and invasiveness (p < 0.05)." (PMID 35326643, 2022). "Combining CDK9 inhibition with DNMT inhibition may thus attain synergistic induction of TSGs and inhibition of tumor growth." (PMID 34207158, 2021). "CDK9 inhibition represents a therapeutically tractable approach for reducing the expression of short‐lived survival factors such as MCL‐1 and subsequently driving apoptosis in tumor cells that depend upon these factors for survival." (PMID 35847704, 2020). "In high-CDK9 TNBC cell lines (MDA-MB-231 and MDA-MB-453), atuveciclib markedly reduced the number and size of colonies in a dose-dependent manner; whereas no such anti-tumor effects were observed for a low-CDK9 TNBC cell line." (PMID 30647871, 2018). "These tumor cells did, however, not respond to CDK9 inhibition when we used the highly specific CDK9 inhibitor LDC000067, previously reported to target MYC." (PMID 29511348, 2018). "We saw that the inhibitory effect was mimicked by suppressing CDK2 by using specific shRNAs and further found that neither TrkA nor CDK9 was involved in the mechanisms of tumor cell suppression." (PMID 29511348, 2018). "Strong and diffuse expression of CDK9 was observed in more than 90% of invasive adenocarcinoma cells in all tumor samples with minimal to absent staining of the stromal cells." (PMID 28404924, 2017). "Inhibition of CDK9, similar to CYC065, was also shown to be critical to tumor suppression." (PMID 29137393, 2017). "Here the authors analyse the response to BH3 mimetics in SCLC, delineate patterns of expression of apoptotic proteins correlated with differential sensitivities and demonstrate a synergistic anti-tumour activity between ABT-199 and anthracyclines or CDK9 inhibitors." (PMID 28714472, 2017). "We also explore the effects of this inhibitor in combination with novel agents, including the BCL-2 inhibitor (Venetoclax), CDK-9 inhibitor (BAY-1143572), and p110δ-PI3K inhibitor (Idelalisib), as a means of uncovering complimentary anti-tumor pathways that can be targeted." (PMID 29383130, 2017). "In line with this notion, our results show that CDK9 inhibition in combination with TRAIL can selectively kill tumor cells, but not PHH within a significant therapeutic window." (PMID 24362439, 2014). "Remarkably, studies conducted on Iron chelators ICL670 and ICL311 reported kinase activity inhibition following the separation of CDK9 from cyclin T1, which, in turn, resulted either in suppression of HIV-1 replication or repression of tumor growth in vitro and in animal models." (PMID 23840966, 2013). "Combination treatment with the CDK9 inhibitor LDC000067 and the BET inhibitor BI 894999 led to a strong reduction in global RNA pol II Ser2 phosphorylation levels and a marked induction of apoptosis in vitro and in vivo, and synergistically induced tumour regression compared to single agents." (PMID 40163908, 2025). "Interestingly, we observed that both CREPT and CDK9 were expressed not only in panCK+ tumor cells but also in other cell types within the tumor microenvironment, suggesting that CREPT and CDK9 may play broader roles beyond tumor cells." (PMID 40860160, 2025).
tumor (continued). "Mechanistically, CDK9 inhibition leads to compensatory activation of ERK‐MYC signaling, accompanied by the recovery of proto‐oncogenes, upregulation of immediate early genes (IEGs), stimulation of the complement C1r‐C3‐C3a cascade, and induction of tumor immunosuppression." (PMID 39254172, 2024). "As predicted, and consistent with the observation that most of the liver tumor cells expressed GFP and the Cdk9 shRNA, Dox treatment reduced the expression of CDK9 and pSer2 in HCC cells, which correlated with a robust reduction of HCC tumor burden as gauged by liver weight after 2 wk on Dox." (PMID 35442775, 2022). "An analysis of 20 pairs of CRC and adjacent non-tumor colon tissue by immunohistochemistry revealed that CDK9 expression was increased significantly in tumor versus non-tumor tissue, suggesting CDK9 as a potentially suitable therapeutic target also in this large tumor entity." (PMID 34535764, 2022). "In fact, gene set enrichment analysis (GSEA) of RNA-sequencing (RNA-seq) data from isolated MYC-expressing Cdk9-suppressed tumor cells (but not controls) showed reversal of signatures associated with MYC expression and ribosome biogenesis as was observed in orthotopic models." (PMID 35442775, 2022). "While the studies presented in this manuscript do not involve the immune system, it is highly likely that CDK9 inhibitors might enhance the anti-tumor immune response, helping to overcome the resistance to the G12C inhibitors." (PMID 34359807, 2021). "The combined effects of BRD4 and CDK9 inhibition on blocking tumor cell proliferation might be independent of the MYC- expression, as H1792 is a MYC-amplified cell line and HeLa cells do not harbour any MYC alteration." (PMID 29156698, 2017). "In addition to its role of triggering transcription elongation, CDK9 enzymatic activity is also required for the maintenance of heterochromatin compaction by a mechanism involving CDK9-mediated phosphorylation of BRG1 and the silencing of tumor suppressor genes." (PMID 35884401, 2022). "The results showed that CDK9 were closely related to lymphocyte infiltration in tumor tissue, such as CD4 + T cells, CD8 + T cells, et, but the expression level of CDK9 was neither increased nor decreased in the CRC." (PMID 35814446, 2022).
hematologic malignancies (29 papers, 2017 to 2026). "The effects of CDK9 have been studied in hematologic malignancies, and many of them have suggested the downregulation of master transcription factor MYC or upregulation of anti-apoptotic molecules such as MCL1 and BCL2." (PMID 40713627, 2025). "CDK7 and CDK9 inhibitors exemplify this strategy and have demonstrated efficacy in hematological malignancies, showing potential for GBM therapy." (PMID 40565099, 2025). "To date, clinical trials of CDK9 inhibitors have been restricted to hematologic malignancies where, despite positive preclinical results, the efficacy as monotherapy in clinical trials has been mostly mediocre." (PMID 37801608, 2024). "VIP-152 is another selective CDK9 inhibitor that shows promising efficacy against hematological malignancies and solid tumors." (PMID 38172923, 2024). "Currently, known mechanisms, such as MCL-1 dysregulation triggered by CDK9 in hematological malignancies and solid tumors, have mainly been discovered using pan-CDK inhibitors." (PMID 37272701, 2023). "Several clinical trials testing CDK9 inhibitors are currently underway in advanced solid and hematologic malignancies." (PMID 36378653, 2022). "Many more CDK9 inhibitors have been preclinically evaluated in a broad range of hematological malignancies." (PMID 34065376, 2021). "We evaluated fadraciclib, a CDK2/CDK5/CDK9 inhibitor which has successfully completed a First-in-Human Phase I clinical trial, and is continuing clinical development in both solid tumors and hematological malignancies." (PMID 34465787, 2021). "So far, AZD4573 is the only selective CDK9 inhibitor invested clinically in hematological malignancies." (PMID 34065376, 2021). "Research findings indicate that innovative CDK9 inhibitors and the silencing of CDK9 through siRNA may drastically change the therapeutic approach to hematological malignancies, particularly for patients facing recurrence or resistance to prior treatments." (PMID 42201387, 2026). "CDK9 has been extensively studied in hematological malignancies." (PMID 37272701, 2023). "This review focuses primarily on hematologic malignancies because they exhibit pronounced transcriptional addiction to short-lived super-enhancer-driven transcripts (MYC, MCL-1), making CDK9 inhibition particularly effective." (PMID 42201387, 2026). "The CDK9 inhibitor, AZD4573, currently in clinical trials for hematologic malignancies, acted synergistically with palbociclib in these ER+in vitro 2D and 3D models." (PMID 37801608, 2024). "CDK9 inhibitors, such as AZD4573 are under clinical investigation in hematologic malignancies (ClinicalTrials.gov Identifier: NCT03263637)." (PMID 39616159, 2024). "In preliminary studies in T-PLL, CDK9 inhibition decreased the expression of JAK/STAT related transcripts, c-Myc, and Mcl-1 [as has been observed in other hematologic malignancies]." (PMID 37569479, 2023). "Recently, fadraciclib, a potent inhibitor of CDK9 showed an ability to repress MYC and is currently in early-phase clinical trials for solid tumors and hematologic malignancies." (PMID 34638300, 2021). "Two of the CDK9 inhibitors used in our studies, SNS032 and AZD4573, have been in clinical trials for hematological malignancies." (PMID 34359807, 2021). "The specificity of additive effects of 9-ING-41 and the CDK9 inhibitor BAY-1143572 to one cell line, SUDHL-4, is reflective of the complexities of GSK-3β interactions with cell cycling pathways in hematologic malignancies." (PMID 29383130, 2017). "These preclinical studies have prompted the clinical testing of AZD4573 in hematologic malignancies and suggest that H3K27M-mutant tumors that are characterized by AFF4 upregulation are candidates for clinical CDK9 inhibition." (PMID 35567477, 2022). "However, the 3rd generation of CDK9 inhibitors (BAY-1251152 and AT-7519) produced promising outcomes in patients with hematological malignancies and solid tumors, which will be evaluated further in future clinical trials." (PMID 35884401, 2022).
hematologic malignancies (continued). "AZD4573 was optimized as a highly selective CDK9 inhibitor with an IC50 of less than 4 nM and exhibited a greater than 10-fold selectivity for CDK9 over CDKs 1–7; it is currently regarded as a clinical candidate for the treatment of hematologic malignancies." (PMID 36248973, 2022).